ZBTB16 (zinc finger and BTB domain containing 16)
Diseases named in the same sentence as ZBTB16 in open-access papers (continued):
Sharing a sentence is not in itself a finding about the gene and the disease.
glioma (7 papers, 2015 to 2024). A benign or malignant brain and spinal cord tumor that arises from glial cells (astrocytes, oligodendrocytes, ependymal cells). "Third, variants in CCDC26 (the 8q24 locus), C2orf80 (close to IDH), LRIG1, PHLDB1, ETFA, MAML2 and ZBTB16 were associated with IDH-mutant glioma." (PMID 31842352, 2019). "Intriguingly, single nucleotide polymorphisms in both the LRIG1 and ZBTB16 genes are associated with glioma susceptibility." (PMID 29317492, 2018). "The relationship between the physical ZBTB16-LRIG1 interaction and the functions of LRIG1 and ZBTB16 in glioma susceptibility remains an important area for future research." (PMID 29317492, 2018). "Risk variants in LRIG1, PHLDB1, ETFA, MAML2 and ZBTB16 were also associated with IDH-mutant glioma." (PMID 31842352, 2019). "Furthermore, we observed a significant association between the genetic variants in LRIG1, PHLDB1, ETFA, ZBTB16 and MAML2 and the risk of IDH-mutant glioma." (PMID 31842352, 2019). "Recently, analysis of 297 glioma samples from the Chinese Glioma Genome Atlas for local immune signature genes identified AIMP1, FOXO3, and ZBTB16 as positive prognostic indicators well correlated with patient overall survival (OS)." (PMID 29379495, 2017). "Collectively POLR3B, ETFA, VTI1A, ZBTB16 and PHLDA1 are altered in 8% (22/286) of LGG as compared with 3% (8/273) of GBM (P=0.014) providing support for these genes having a role in glioma tumorigenesis." (PMID 26424050, 2015). "ZBTB16 gene expression has been observed to have a distinct expression pattern associated with GBM prognosis, but no clear role has so far been observed for lower grade glioma tumors." (PMID 31842352, 2019).
Insulin resistance (6 papers, 2014 to 2022). Increased resistance towards insulin, that is, diminished effectiveness of insulin in reducing blood glucose levels. "In our model, it is possible that changes in the level of Zbtb16 contributed to the increased hepatic glucose production and insulin resistance phenotypes in HFD PN offspring." (PMID 34977118, 2021). "Adenovirus-mediated overexpression of Zbtb16 led to increased hepatic gluconeogenic gene expression, hyperinsulinemia, and insulin resistance in mice." (PMID 34977118, 2021).
diabetes (5 papers, 2017 to 2025). "Increasing studies have highlighted that ZBTB16 expression correlates with diabetes through the adaptive thermogenesis response, mitochondrial respiration promotion, and regulation of the insulin signaling pathway." (PMID 34802056, 2021). "T1D mouse models with Fbw7 overexpression, or simultaneously with Zbtb16 suppression using shRNA were established and checked for diabetes incidence." (PMID 34802056, 2021). "Increased Zbtb16 gene expression has been observed in multiple models of diabetes, including db/db, streptozotocin (STZ) treated, and HFD-fed mice." (PMID 34977118, 2021).
hepatocellular carcinoma (5 papers, 2017 to 2024). A malignant tumor that arises from hepatocytes. "ZBTB16, also named as PLZF, has previously been shown to be down-regulated in hepatocellular carcinoma, which supports our current study that ZBTB16 was down-regulated in liver cancer specimens compared to non-tumor liver specimens." (PMID 28740751, 2017).
COVID-19 (4 papers, 2021 to 2024). A disease caused by infection with severe acute respiratory syndrome coronavirus 2. "The other genes at 11q14.2 locus may also be relevant to COVID-19, such as zinc finger and BTB domain containing 16 (ZBTB16)." (PMID 34465742, 2021). "We found the upregulation of TLE1, MAL and ZBTB16 in the tears of COVID-19 patients." (PMID 34615949, 2021). "Similarly, we found the relevant evidence of alteration or association of transcription factors CENPA, DDIT3, JUNB, TFDP1, ZBTB16, ZNF467 for the alteration of diverse cellar process and function to develop the COVID-19 pathogenesis and associated respiratory disorders." (PMID 38365632, 2024).
non-small cell lung carcinoma (4 papers, 2017 to 2025). A group of at least three distinct histological types of lung cancer, including non-small cell squamous cell carcinoma, adenocarcinoma, and large cell carcinoma. "The tumour suppressor ZBTB16 was found to be downregulated in non-small-cell lung cancer, decreased expression levels may contribute to cell survival, and overexpression was found to increase apoptosis and inhibit proliferation." (PMID 32817744, 2020). "ZBTB16 was also down-regulated in never smoker patients with lung adenocarcinoma and non-small cell lung cancer high-metastatic cell line compared with the low-metastatic cell line." (PMID 32998690, 2020).
acute leukemia (3 papers, 2010 to 2024). A clonal (malignant) hematopoietic disorder with an acute onset, affecting the bone marrow and the peripheral blood. "In module 3, the results indicated that RUNX1, ZBTB16, GATA2 and MEIS1 which involved in the myeloid cell differentiation and the pathogenesis of acute leukemia showed higher levels of expression in cells from the MDS across differentiation." (PMID 38632656, 2024).
asthma (3 papers, 2022 to 2025). "Among them, PDK4, FKBP5, ZBTB16, WNT5A, GMPR and WIF1 are reported to be associated with asthma in the previous researches." (PMID 36550577, 2022). "PDK4 (P-value < 0.001) and ZBTB16 (P-value < 0.01) were up-regulated in asthma group, while WNT5A (P-value < 0.05), NR4A3 (P-value < 0.001) and WIF1 (P-value < 0.05) were down-regulated." (PMID 36550577, 2022).
autism spectrum disorder (3 papers, 2021 to 2023). A spectrum of developmental disorders that includes autism, and Asperger syndrome. "A further mechanistic study found that the Zbtb16 transcriptome included genes involved in neocortical maturation and autism spectrum disorder, and schizophrenia pathobiology." (PMID 37511534, 2023). "Zbtb16 knockout mice show several behavioral impairments relevant to neurodevelopmental disorders such as autism spectrum disorder and schizophrenia." (PMID 36039298, 2022). "Using genomics approaches, we identified the Zbtb16 transcriptome that includes genes involved in neocortical maturation such as neurogenesis and myelination, and both autism spectrum disorder (ASD) and schizophrenia (SCZ) pathobiology." (PMID 33895774, 2021).
autoimmune disease (3 papers, 2018 to 2019). A disorder resulting from loss of function or tissue destruction of an organ or multiple organs, arising from humoral or cellular immune responses of the individual to their own tissue constituents. "Hence, our data reveals the ZBTB16 DMP as a prominent epigenetic biomarker for GC treatment, and future studies should assess its utility in predicting clinical GC response in patients with inflammatory or autoimmune diseases receiving GC therapy." (PMID 31064978, 2019).
Cognitive impairment (3 papers, 2021 to 2023). Abnormal cognition is characterized by deficits in thinking, reasoning, or remembering. "Zbtb16-deficient mice showed social impairment, repetitive behaviors, risk-taking behaviors, and cognitive impairment." (PMID 37511534, 2023). "Here we show the deletion of Zbtb16 in mice leads to social impairment, repetitive behaviors, risk-taking behaviors, and cognitive impairment." (PMID 33895774, 2021). "On the other hand, Zbtb16 KO mice showed social and cognitive impairment, as well as risk-taking behaviors, which are all behaviors relevant to SCZ." (PMID 33895774, 2021). "In this study, we demonstrate the role of Zbtb16 in ASD-like and SCZ-like behaviors such as social impairment, repetitive behaviors, risk-taking behaviors, and cognitive impairment." (PMID 33895774, 2021). "Zbtb16 KO mice displayed ASD-like behaviors such as social impairment and increased repetitive behaviors as well as cognitive impairment." (PMID 34795694, 2021).
Hepatic steatosis (3 papers, 2018 to 2022). Steatosis is a term used to denote lipid accumulation within hepatocytes. "Hepatic Zbtb16 is upregulated in several murine models showing severe hepatic steatosis." (PMID 29731739, 2018).
Hyperglycemia (3 papers, 2014 to 2022). An increased concentration of glucose in the blood. "Liver-specific knockdown of Zbtb16 relieved hyperglycemia in db/db mice and led to decreased insulin levels, improved glucose and pyruvate tolerance, and insulin sensitivity." (PMID 33061941, 2020). "Very recently, hepatic knockdown of Zbtb16 was shown to ameliorate hyperglycemia in db/db mice." (PMID 25403085, 2014).
Infertility (3 papers, 2014 to 2021). "In mice, complete knockout of Zbtb16 as well as spontaneous mutation (luxoid) lead to infertility and number of skeletal patterning defects." (PMID 25403085, 2014).
metastatic tumor (3 papers, 2016 to 2023). "Zbtb16 was previously implicated as a candidate due to its membership in a proliferation-associated gene network that is predictive of metastatic disease." (PMID 27074153, 2016).
Micropenis (3 papers, 2018 to 2020). "We suggest that ZBTB16 and its co-expressed lnc-ZBTB16 might be the primary target of oestrogen that induces micropenis." (PMID 30598023, 2018).
schizophrenia (3 papers, 2021 to 2023). A major psychotic disorder characterized by abnormalities in the perception or expression of reality. "Among them, PARP1 and ZBTB16 were implicated in the pathogenesis of schizophrenia." (PMID 37511534, 2023).
viral infection (3 papers, 2017 to 2025). "Notably, we discovered upregulation of multiple ISGs, such as ZBTB16, MX1, OASL, RSAD2, CMPK2, and CXCL14 in the DiMNF treated primary cells, even in the absence of viral infection." (PMID 37672505, 2023).
alcoholic hepatitis (2 papers, 2019 to 2025). Acute hepatitis resulting from ingestion of alcohol. "The hepatic expression of transcription factors that control the differentiation of MAIT cells such as RORC/RORγt, ZBTB16/PLZF, Eomes in patients with severe alcoholic hepatitis were lower than that from healthy individuals." (PMID 31244862, 2019).
cervical carcinoma (2 papers, 2021 to 2023). A carcinoma arising from either the exocervical squamous epithelium or the endocervical glandular epithelium. "Although ZBTB16 has an unclear function for uterine cancer, a previous study revealed that overexpression of ZBTB16 inhibited proliferation in cervical carcinoma cells and induced apoptosis." (PMID 34489442, 2021). "High expression of MYH1, MYH4, FGG, DEPP1, and ZBTB16 was associated with shorter overall survival of patients with cervical cancer; high expression of SULT1E1, RAB3C, CXCR3, and PROX2 was associated with longer overall survival of patients with cervical cancer." (PMID 37350944, 2023).
cholangiocarcinoma (2 papers, 2017 to 2022). A carcinoma that arises from the intrahepatic biliary tree (intrahepatic cholangiocarcinoma) or from the junction, or adjacent to the junction, of the right and left hepatic ducts (hilar cholangiocarcinoma). "The ZBTB16 gene is active in the blocking of differentiation; thus, methylation-driven abnormalities in ZBTB16 may lead to cholangiocarcinoma." (PMID 28178311, 2017). "Examining cholangiocarcinoma, we observed that the HRAS, KIT, ZBTB16, FAS and NCOA4 genes were altered by high methylation (shown in light sea green)." (PMID 28178311, 2017).
Crohn disease (2 papers, 2018 to 2025). A gastrointestinal disorder characterized by chronic inflammation involving all layers of the intestinal wall, noncaseating granulomas affecting the intestinal wall and regional lymph nodes, and transmural fibrosis. "ZBTB16 also contains a site differentially methylated in Crohn’s disease." (PMID 41010012, 2025).
endometriosis (2 papers, 2019 to 2025). The growth of functional endometrial tissue in anatomic sites outside the uterine body. "However, blocking mPRβ expression results in a more than 70% reduction in ZBTB16 expression, reinforcing the notion that mPRβ is essential for decidualization in cells from healthy women and those with endometriosis." (PMID 40806428, 2025). "Both Org OD 02-0 concentrations mimicked the effects of P4 by upregulating the expression of IGFBP1, PRL, HAND2, and ZBTB16 in control, eutopic, and ectopic cells from women with endometriosis, suggesting the involvement of mPRs in the decidualization process of endometrial cells." (PMID 40806428, 2025). "Interestingly, in the case of the decidualization marker ZBTB16, none of the tested concentrations of Org OD 02-0 replicated the effect of P4 in control, eutopic or ectopic cells derived from women with or without endometriosis." (PMID 40806428, 2025).
gastric cancer (2 papers, 2021 to 2023). A primary or metastatic malignant neoplasm involving the stomach. "This study is the first to demonstrate the suppressive role of ZBTB16 silencing in gastric cancer and present a novel regulatory relationship between ISLR and MGAT5 in gastric cancer." (PMID 37427332, 2023). "All genes except GPX3, ZBTB16, and KCNQ1 have OR of >1 for gastric cancer, whereas all genes have OR of >1 for Parkinson’s disease, suggesting that for a patient who has either Parkinson’s disease or gastric cancer, the status of 12 genes is highly likely to be un-silenced." (PMID 33596182, 2021).
Huntington disease (2 papers, 2015 to 2018). Huntington disease (HD) is a rare neurodegenerative disorder of the central nervous system characterized by unwanted choreatic movements, behavioral and psychiatric disturbances and dementia. "G-4 genes included 6 genes: Btg3 associated nuclear protein (Banp), Ephx2, retinoid X receptor gamma (Rxrg), Ryr1, RNA-binding protein fox-1 homolog 1 (Rbfox1) and Zbtb16 categorized as ‘hereditary disorder (Huntington's disease)'." (PMID 26165378, 2015). "In the present study, we investigated gene expression profiles in the kidneys, and unexpectedly found that 6 SHRSP-specific genes isolated from the rats at 6 weeks of age (Banp, Ephx2, Rbfox1, Rxrg, Ryr1 and Zbtb16) were annotated to ‘Huntington's disease'." (PMID 26165378, 2015). "This is accompanied by reduced autophagy (accumulation of p62) as the consequence of increased ZBTB16 expression and reduced ULK1 activity, as we have previously observed in Huntington’s disease (HD)." (PMID 29631635, 2018).
leiomyoma (2 papers, 2017 to 2021). A well-circumscribed benign smooth muscle neoplasm characterized by the presence of spindle cells with cigar-shaped nuclei, interlacing fascicles, and a whorled pattern. "Lastly, we confirmed that levels of transcript encoding HES6 (P < 0.05), ZBTB16 (P < 0.02), ITPKA (P < 0.05), and CORIN (P < 0.05) were significantly higher in specimens of luteal phase leiomyomas than proliferative phase specimens." (PMID 28637297, 2017). "Previous studies have found that ZBTB16 can be used to distinguish leiomyosarcomas from leiomyomas." (PMID 34660783, 2021).
liver cancer (2 papers, 2017 to 2023). An epithelial or non-epithelial malignant neoplasm that arises from the liver. "In the current study, we have also identified few genes that are co-regulated with DAPK1, especially for SLC16A3, PCOLCE and ZBTB16, since the expression of these genes were dysregulated in liver cancer." (PMID 28740751, 2017). "DAPK1 expression was positively correlated with IRF2, IL7R, PCOLCE and ZBTB16, and negatively correlated with SLC16A3 in both liver cancer datasets." (PMID 28740751, 2017). "Among these genes, PCOLCE and ZBTB16 were significantly down-regulated, while SLC16A3 was significantly upregulated in liver cancer." (PMID 28740751, 2017).
liver fibrosis (2 papers, 2022 to 2023). "In particular, the expression of Zbtb16 (zinc finger and BTB domain-containing 16) was significantly decreased by Glrx administration, suggesting that Zbtb16 may be a key downstream effector controlling liver fibrosis." (PMID 35624731, 2022).
malignant mesothelioma (2 papers, 2014 to 2020). A malignant neoplasm of the pleura or peritoneum, arising from mesothelial cells. "Additionally, malignant mesothelioma cell data indicated that the downregulation of ZBTB16 might promote cell survival." (PMID 32817744, 2020).
myelocytic leukaemia (2 papers, 2016 to 2017). "The pathways and genes that significantly changed were classified as follows: cancer pathways (EPAS1, CCND1, FGF13), myeloid leukemia pathways (ZBTB16, KIT, IL13), hematopoietic cell lineage pathways (EPOR, GYPA, CD36) and so on." (PMID 27516205, 2016).
osteoporosis (2 papers, 2020 to 2023). A condition of reduced bone mass, with decreased cortical thickness and a decrease in the number and size of the trabeculae of cancellous bone (but normal chemical composition), resulting in increased fracture incidence. "Bone-targeting ZBTB16 overexpression had a therapeutic effect on the decreased bone density and remodeling capacity of Brd4fl/flPrx1-cre mice and osteoporosis (OP) models." (PMID 37280207, 2023). "Therefore, our study shows that SEs orchestrate the osteogenesis of MSCs by targeting ZBTB16 expression, which provides an attractive focus and therapeutic target for osteoporosis." (PMID 37280207, 2023).
sarcoma (2 papers, 2019 to 2025). A usually aggressive malignant neoplasm of the soft tissue or bone. "One clear cell sarcoma presented with a weak membranous expression and nuclear expression was seen in one MPNST (weak, score 1) as well as one intimal sarcoma with a strong expression harboring a ZBTB16::ABL1 fusion." (PMID 40232379, 2025).
sarcopenia (2 papers, 2024 to 2026). Progressive decline in muscle mass due to aging which results in decreased functional capacity of muscles. "By using ML algorithms and expression analysis techniques, this study further validated several URGs including CBLB, PSMD6, RNF115, SMAD3, UCHL3 and ZBTB16 as potential markers associated with sarcopenia." (PMID 41560007, 2026). "In the sarcopenia dataset, BTG2 (AUC = 0.867), CDKN1A (AUC = 0.892), CEBPB (AUC = 0.942), DDIT4 (AUC = 0.792), FOXO3 (AUC = 0.900), NFKBIA (AUC = 0.892), ZBTB16 (AUC = 0.808) and ZFP36 (AUC = 0.775) demonstrated better diagnostic efficacy in distinguishing sarcopenia patients from healthy controls." (PMID 38962732, 2024). "Together these findings suggest that ZBTB16 and RNF15 may represent previously unrecognized regulators in sarcopenia and should be further investigated." (PMID 41560007, 2026). "Although ZBTB16 and RNF15 are not yet directly linked to sarcopenia, current evidence suggests that they participate in biological pathways relevant to muscle metabolism and proteostasis." (PMID 41560007, 2026).
yolk sac tumor (2 papers, 2023 to 2024). A non-seminomatous malignant germ cell tumor composed of primitive germ cells. "ZBTB16 also shows high sensitivity and specificity for yolk sac tumors and was found to be expressed in 91.6% of extra-gonadal and metastatic yolk sac tumors." (PMID 37138865, 2023).
breast tumor (1 paper, 2020). "To address whether methylation occurs in primary tumors, we analyzed the methylation status of ZBTB16 in 152 breast tumor samples and 16 normal breast tissues using MSP." (PMID 32517789, 2020).
calcification (1 paper, 2022). Process by which organic tissue becomes hardened by the physiologic deposit of calcium salts. "Based on proteomics and transcriptomics data, we detected several proteins which have been less studied in cardiovascular calcification, including ZBTB16 (PLZF)." (PMID 36407442, 2022).
central serous chorioretinopathy (1 paper, 2025). "In fact, our initial experiments were based on the hypothesis that ZBTB16 may be a mediator of glucocorticoid effects in central serous chorioretinopathy (CSC)." (PMID 40540650, 2025).
coagulopathy (1 paper, 2022). "This variant shares common features with ZBTB16-RARA AML: a moderate incidence of coagulopathy, resistance to ATRA and ATO, and poor outcome." (PMID 35494081, 2022).